FPR1 (formyl peptide receptor 1)
Diseases named in the same sentence as FPR1 in open-access papers (continued):
Sharing a sentence is not in itself a finding about the gene and the disease.
autoimmune disease (2 papers, 2021). A disorder resulting from loss of function or tissue destruction of an organ or multiple organs, arising from humoral or cellular immune responses of the individual to their own tissue constituents. "We also suggest FPR1 as a major target to control DCs for the treatment of autoimmune diseases." (PMID 34378309, 2021).
brain ischemia (2 papers, 2022 to 2023). Diminished or absent blood supply to the brain caused by obstruction (thrombosis or embolism) of an artery resulting in neurologic damage. "These fpr1-/- mice had better neurological outcomes and less spleen weight loss than wild-type mice after brain ischemia." (PMID 35547761, 2022). "cFLFLF, an antagonist for FPR1, reduced the migration of the peripheral cells into the brain and improved neurological outcome after brain ischemia." (PMID 35547761, 2022). "Cells that are positively stained for both CD68 and FPR1 in the spleen of a mouse with brain ischemia were increased dramatically after reperfusion." (PMID 35547761, 2022). "There was an increase in MCP1, IL-1β and IL-6 in the spleen of wild-type mice and fpr1-/- mice and IL-1β and IL-6 in the brain of wild-type mice after brain ischemia." (PMID 35547761, 2022). "fpr1-/- mice had an attenuated peripheral monocyte and neutrophil infiltration into the brain, a reduced proinflammatory cytokine level and an improved neurological outcome compared with wild-type mice after brain ischemia." (PMID 35547761, 2022). "Based on the role of FPR1 in inflammation, we hypothesize that FPR1 plays a critical role in splenocyte migration into the brain and that cFLFLF provides neuroprotection by inhibiting migration of peripheral cells including splenocytes into the brain after brain ischemia." (PMID 35547761, 2022). "The change of FPR1 expression in the monocytes, macrophages and neutrophils after brain ischemia has not been reported." (PMID 35547761, 2022). "Although brain ischemia and reperfusion increased proinflammatory cytokine production in the spleen of both wild-type and fpr1-/- mice, this increased cytokine production occurred in the ischemic brain tissues of wild-type mice but not fpr1-/- mice." (PMID 35547761, 2022).
colorectal adenocarcinoma (2 papers, 2022 to 2025). The most common type of colorectal carcinoma. "Data on 594 colorectal adenocarcinoma revealed that FPR1 mRNA levels significantly and directly correlated with mRNA expression levels of the proresolving factors ALOX5 and ALOX15B." (PMID 35808840, 2022).
liver cancer (2 papers, 2020 to 2023). An epithelial or non-epithelial malignant neoplasm that arises from the liver. "The tumorigenicity of human liver cancer cells in immuno-compromised mice was markedly diminished by FPR1 knockdown." (PMID 32038501, 2020). "Similar to observations in human GBM, FPR1 is detected in human liver cancer cells to promote cell migration, invasion, proliferation and production of angiogenic factors." (PMID 32038501, 2020).
multiple sclerosis (2 papers, 2022 to 2024). A progressive autoimmune disorder affecting the central nervous system resulting in demyelination. "Research indicates that FPR1‐mediated microglia/macrophage activation exacerbates the progression of various CNS disorders including epilepsy, cerebral hemorrhage, and multiple sclerosis." (PMID 39654367, 2024). "Therefore, FPR1 is an essential component of innate immunity in chronic degenerative diseases such as multiple sclerosis." (PMID 36237611, 2022).
myeloid leukemia (2 papers, 2011 to 2022). A clonal proliferation of myeloid cells and their precursors in the bone marrow, peripheral blood, and spleen. "Therefore, in myeloid leukemia cells GEF-H1 regulates motility, but not FPR1-regulated directional sensing." (PMID 36341452, 2022).
Parkinson disease (2 papers, 2025). A progressive degenerative disorder of the central nervous system characterized by loss of dopamine producing neurons in the substantia nigra and the presence of Lewy bodies in the substantia nigra and locus coeruleus. "FPR1 was enriched in 79 pathways, including ribosome, leishmania infection, Parkinson’s disease, cytokine-cytokine receptor interaction, and chemokine signaling." (PMID 40630963, 2025). "ε-Viniferin had an anti-inflammatory effect via the targeting of formyl peptide receptor 1 in human neutrophils, and Sirtuin 3 (SIRT3)-mediated neuroprotective effects in Huntington’s disease models and Parkinson’s disease models caused by rotenone administration of SH-SY5Y cells." (PMID 40141054, 2025). "Further analysis of the signaling pathways involving CD163, FPR1, and VSIG4 revealed that CD163 was enriched in 76 pathways, including ribosome, Parkinson’s disease, leishmania infection, Fc gamma R-mediated phagocytosis, and B cell receptor signaling." (PMID 40630963, 2025).
plague (2 papers, 2013 to 2020). Plague is a severe bacterial infection caused by the gram-negative bacterium Yersinia pestis. "Thus it is conceivable that infection of epidemic bacterialplagues, such as cholera, salmonella, bubonic plague, tuberculosis and pertussis might have createdselective pressure on the evolution of the FPR1 gene." (PMID 23373827, 2013). "Thus, despite the putative role of ail in Y. pestis adherence in vitro and LcrV binding to FPR1, our data suggest that these surface structures do not individually play a major role in mediating Y. pestis adherence in the lung early during primary pneumonic plague." (PMID 32759339, 2020).
psoriasis (2 papers, 2020 to 2025). An autoimmune condition characterized by red, well-delineated plaques with silvery scales that are usually on the extensor surfaces and scalp. "Neutrophil-associated genes were decreased (Fpr1 and Sirpb1b) at d7 compared with d3 among KC36-dependent genes, consistent with the important reduction of neutrophil infiltration and with a switch from innate to adaptive immunity in Aldara-induced psoriasis-like dermatitis." (PMID 32345660, 2020). "Studies have indicated that the alteration of FPR1 function using natural compounds like 3β-hydroxyurs-12,18-dien-28-oic acid (randialic acid B, RAB) and 3β-hydroxyurs-12,19-dien-28-oic acid (tomentosolic acid, TA), has the potential to mitigate in vivo psoriasis-like inflammation." (PMID 40540498, 2025).
pulmonary oedema (2 papers, 2017 to 2024). "As alveolar epithelial and endothelial cell function plays an important contributory role in the development of pulmonary oedema in acute lung injury, we sought to determine the contribution of parenchymal FPR1 function in this process." (PMID 28469031, 2017).
renal fibrosis (2 papers, 2020 to 2023). A final common manifestation of a wide variety of chronic kidney diseases characterized by glomerulosclerosis and tubulointerstitial fibrosis. "To determine the role of FPR-1 in renal fibrosis, we utilized the unilateral ureteral obstruction (UUO) model of kidney injury, whereby surgical ligation of the ureter of the left kidney triggers an increase in hydrostatic pressure driving damage, inflammation, and ultimately fibrosis." (PMID 32102985, 2020). "Taken together, these data suggest that FPR-1 is not required for initiation or progression of renal fibrosis in the UUO model." (PMID 32102985, 2020).
sarcoma (2 papers, 2017 to 2019). A usually aggressive malignant neoplasm of the soft tissue or bone. "Accordingly, RI-3 is a nanomolar competitor of N-formyl-Met-Leu-Phe for binding to FPR1 and inhibits migration, invasion, trans-endothelial migration of sarcoma cells and VEGF-triggered endothelial tube formation." (PMID 28465589, 2017).
schwannoma (2 papers, 2018 to 2020). A benign, usually encapsulated slow growing tumor composed of Schwann cells. "Although we used a specific anti-Fpr2 antibody, we cannot rule out a contribution of Fpr1 in the reaction of RT4 schwannoma cells to the fMLF effect." (PMID 33322305, 2020).
tuberculosis (2 papers, 2013 to 2024). A chronic, recurrent infection caused by the bacterium Mycobacterium tuberculosis. "This study investigates the functions of Fpr1 and Fpr2 in defense against Mycobacterium tuberculosis (Mtb), the causative agent of TB." (PMID 38853986, 2024).
ulcers (2 papers, 2012 to 2023). "Our results showing the presence of copious numbers of neutrophils and larger ulcers in FPR1−/− mice may be related to a reduction in these anti-inflammatory activities of annexin A1, leading us to examine annexin A1 levels in the mice." (PMID 22383080, 2012).
viral infection (2 papers, 2012 to 2025). "Since both of these stimuli increase FPR1 expression it is tempting to speculate that FPR1 may have a role in host responses to viral infections in addition to its proposed role in fighting bacterial infection." (PMID 23185575, 2012).
abdominal aortic aneurysm (1 paper, 2025). Enlargement and ballooning of the vessel that supplies arterial blood to the abdomen, pelvis and legs. "FAM3D functions as a chemotactic agonist for the G protein-coupled receptors FPR1 and FPR2, strongly attracting immune cells such as neutrophils and monocytes, thereby contributing to the pathogenesis of abdominal aortic aneurysms." (PMID 41465269, 2025).
ascending aortic aneurysm (1 paper, 2025). "Therefore, targeting FPR1 or ICD-related pathways may be a potential strategy for the treatment of ascending aortic aneurysm." (PMID 40630963, 2025).
brain infarct (1 paper, 2022). "Mice with fpr1-/- had reduced brain infarct volume, decreased neurological deficit scores and improved performance on rotarod compared with wild-type mice after a 1.5 h MCAO and 24 h reperfusion." (PMID 35547761, 2022).
brain inflammation (1 paper, 2020). "Several studies demonstrated that Fpr1- and/or Fpr2-deficient mice are protected from neuronal pathologies, among studies to experimental demyelination or lipopolysaccharide-induced brain inflammation." (PMID 33121515, 2020).
bronchopulmonary dysplasia (1 paper, 2021). Bronchopulmonary dysplasia is a chronic respiratory disease that results from complications related to lung injury during the treatment of infant acute respiratory distress syndrome in low-birth-weight premature infants or from abnormal lung development in older infants. "Moreover, recent studies revealed FPR-1 played a critical role in regulating lung inflammation and injuries in bronchopulmonary dysplasia and it also has been demonstrated that FPR-1 can reduce lung injury by mediating neutrophil recruitment in endotoxin-induced ALI." (PMID 33981222, 2021).
brucellosis (1 paper, 2024). Brucellosis is a bacterial infection that spreads from animals to people via unpasteurized dairy products or by exposure to contaminated animal products or infected animals. "As the major contributor of potential inflammatory storm, many inflammatory response genes (e.g., ITGB2, OSM, FPR1, CEBPB, NINJ1) and canonical pro‐inflammatory cytokines (e.g., CXCL8, CCL3, CCL4, TNF, IL1B, S100A12) were expressed at higher levels in brucellosis patients than in healthy donors." (PMID 39135683, 2024).
Cognitive impairment (1 paper, 2022). Abnormal cognition is characterized by deficits in thinking, reasoning, or remembering. "Interestingly, microglia from APP/PS1 mice show an increase in the murine FPR1 and FPR2, and treatment of APP/PS1 mice with a competitive FPR inhibitor ameliorated cognitive impairment, reduced plaque load, and lessened microglial reactivity." (PMID 36359817, 2022).
cyst (1 paper, 2018). A sac-like closed membranous structure that may be empty or contain fluid or amorphous material. "Probably the reduced neo-angiogenesis is responsible for the smaller cyst diameter found in Fpr1 KO mice." (PMID 30140375, 2018). "WT and Fpr1 KO mice did not showed a different number of cyst, but cyst size was smaller in Fpr1 KO mice compared to control animals (P < 0.05)." (PMID 30140375, 2018).
dementia (1 paper, 2023). Loss of intellectual abilities interfering with an individual's social and occupational functions. "As a G protein-coupled receptor, FPR1 is distributed in various immune cells such as macrophages, monocytes, dendritic cells, and neutrophils while it has been shown to be involved in several neurological diseases, including intracerebral hemorrhage, dementia, and traumatic brain injury." (PMID 37180174, 2023).
diabetic nephropathy (1 paper, 2024). "Formyl peptide receptor 1 (FPR1) is abundant in neutrophils and regulates intracellular calcium, which plays a crucial role in diabetic nephropathy." (PMID 39064752, 2024).
endothelial dysfunction (1 paper, 2019). In vascular diseases, endothelial dysfunction is a systemic pathological state of the endothelium (the inner lining of blood vessels) and can be broadly defined as an imbalance between vasodilating and vasoconstricting substances produced by (or acting on) the endothelium. "Further investigation with gain or loss of function method is required to establish the cause and effect relationship between endothelial dysfunction and aberrant FPR1/2/3 expressions." (PMID 31116781, 2019). "Thus, our findings open the possibility of using synthetic FPR1 antagonists and FPR2/FPR3 agonists to resolve persistent inflammation and subsequent endothelial dysfunction in OSA." (PMID 31116781, 2019).
gastric adenocarcinoma (1 paper, 2023). "The most potent compounds were also used to study the role of FPR1 blockade on cell vitality and invasiveness of the gastric adenocarcinoma cell lines AGS and NCl–N87." (PMID 37839346, 2023). "We first assessed the expression levels of FPR1 and FPR2 mRNA in four GC cell lines, i.e., HGC27, derived from human gastric carcinoma, KATOIII, AGS, and NCl–N87, derived from human gastric adenocarcinoma." (PMID 37839346, 2023).
Hepatic steatosis (1 paper, 2020). Steatosis is a term used to denote lipid accumulation within hepatocytes. "Hepatic steatosis, as characterized by the number of lipid droplets and total lipid area, and fibrosis, as characterized by an increase in the percentage area positive for Picrosirius red and αSMA or fibrogenic gene expression, were comparable between C57BL/6 and fpr1–/– mice in the MCD diet model." (PMID 32102985, 2020).
Hypercholesterolemia (1 paper, 2025). An increased concentration of cholesterol in the blood. "FPR1 contributes to atherosclerotic lesions by modulating the number of blood neutrophils under hypercholesterolemia and exacerbates myocardial cell apoptosis and inflammation during ischemia-reperfusion through the MAPK signaling pathway." (PMID 40630963, 2025).
hypersomnia (1 paper, 2019). A sleep disorder characterized by excessive sleepiness. "We speculate that chronic IHR-induced FPR1 over-expression on neutrophil may lead to pro-inflammatory responses and subsequent pronounced hypersomnia in OSA." (PMID 31116781, 2019).
injury (1 paper, 2024). Damage inflicted on the body as the direct or indirect result of an external force, with or without disruption of structural continuity. "Moreover, FPR1 has anti-inflammatory and anti-apoptotic roles in acute liver injury, although its role in chronic liver damage such as NAFLD is not yet clear." (PMID 39700090, 2024).
latent infection (1 paper, 2024). "This analysis revealed that patients with active TB expressed higher levels of FPR1 and FPR2 compared to those with latent infection, suggesting that these receptors are induced by Mtb infection, and their expression correlates with symptomatic disease." (PMID 38853986, 2024).
lung adenocarcinoma (1 paper, 2023). A carcinoma that arises from the lung and is characterized by the presence of malignant glandular epithelial cells. "Our previous study found that the inhibition of FPR1 prevented lung adenocarcinoma cell invasion and migration." (PMID 37747648, 2023).
malignant glioma (1 paper, 2006). A grade III or grade IV glioma arising from the central nervous system. "One of the possible candidates located in this chromosome could be FPR1 due to this gene is expressed in malignant glioma and appears to mediate motility, growth, and angiogenesis of GBM." (PMID 17002787, 2006).
metastasis (1 paper, 2022). The spread or migration of cancer cells from one part of the body (where they first appeared) to another. "The association between lymph node positive recurrence-free patient survival and distant metastasis-free patient survival and ANXA1 and FPR1 and FPR2 expression was examined using TCGA datasets." (PMID 35382852, 2022).
pneumococcal infection (1 paper, 2024). Infections with bacteria of the species streptococcus pneumoniae. "We therefore compared WT, FPR1-, and FPR2-KO infected, either infected or uninfected, with or without Ac2-26 treatment 30 h after pneumococcal infection." (PMID 39768195, 2024).
pulmonary TB (1 paper, 2024). "We observed that expression levels of FPR1 and FPR2 in peripheral blood cells were elevated in patients with active pulmonary TB compared to healthy controls (HCs)." (PMID 38853986, 2024).
rectal cancer (1 paper, 2024). A primary or metastatic malignant neoplasm that affects the rectum. "The pharmacologic inhibition of FPR1 decreased T cell migration and infiltration into tumour microenvironments in most patients with locally advanced rectal cancer harbouring the CC genotype (E346A) of FPR1, highlighting it as an independent predictor." (PMID 38213773, 2024).
relapsing-remitting multiple sclerosis (1 paper, 2013). The most common clinical variant of multiple sclerosis, characterized by recurrent acute exacerbations of neurologic dysfunction followed by partial or complete recovery. "Patients with relapsing-remitting multiple sclerosis (RRMS) have an increased number of neutrophils that regulated phenotypic changes such as reduction of apoptosis and higher expression of TLR2, FPR1, CXCR1, and CD43." (PMID 24174969, 2013).
rheumatic diseases (1 paper, 2025). "Collectively, these findings highlight FPR1‐mediated neutrophil activation as a critical factor in rheumatic diseases, though its role in ILD comorbidity remains unclear." (PMID 41088837, 2025).
Senile plaques (1 paper, 2025). Senile plaques are extracellular deposits of amyloid in the gray matter of the brain. "Furthermore, FPR1 is highly expressed in microglia that infiltrate senile plaques within the brain tissues of AD patients, suggesting that inhibiting FPR activity leads to protective effects on AD." (PMID 40733247, 2025).
serous adenocarcinoma (1 paper, 2019). An adenocarcinoma that is characterized by the presence of papillary patterns and cellular budding. "Thus, we analyzed the uPAR and FPR1 expression on formalin-fixed paraffin-embedded sections from five serous adenocarcinoma tissues by IHC." (PMID 31703596, 2019).
serous ovarian cancers (1 paper, 2019). "Because it has been reported that fallopian tube epithelium gives rise to serous ovarian cancers, we are planning to analyze in-depth the expression levels of FPR1 in areas adjacent to the EOC tissues." (PMID 31703596, 2019).
skin infection (1 paper, 2012). An inflammatory process affecting the skin, caused by bacteria, viruses, parasites, or fungi. "Therefore, in addition to having higher in vivo bacterial burden, mice deficient in TLR2, NOD2 and FPR1 also had decreased IL-1β production and neutrophil recruitment during a S. aureus skin infection in vivo." (PMID 23209417, 2012). "Thus, we evaluated TLR2-, NOD2-, or FPR1-deficient mice in response to S. aureus skin infection and found that each of these mice had impaired IL-1β production and neutrophil recruitment after S. aureus skin infection." (PMID 23209417, 2012). "To investigate whether these PRRs contributed to IL-1β production and neutrophil recruitment during a S. aureus skin infection in vivo, we inoculated wt mice and mice deficient in TLR2, NOD2 or FPR1 with S. aureus." (PMID 23209417, 2012).